TRRAP (transformation/transcription domain associated protein)
Diseases named in the same sentence as TRRAP in open-access papers (continued):
Sharing a sentence is not in itself a finding about the gene and the disease.
microcephaly (1 paper, 2021). A congenital or acquired developmental disorder in which the circumference of the head is smaller than normal for the person's age and sex. "Because trrap-mutant zebrafish partly recapitulate craniofacial malformations, including microcephaly, observed in patients with genetic TRRAP mutations, we propose that trrap-mutant zebrafish are a useful disease model for human TRRAP gene mutations." (PMID 34934055, 2021). "Because the trrap-mutant zebrafish exhibited tooth hypoplasia, small eyes and head, and short ventral pharyngeal arches, we proposed that the functional impairment of the human TRRAP and zebrafish trrap genes causes craniofacial abnormalities, including microcephaly." (PMID 34934055, 2021). "The patients with different missense mutations in human TRRAP gene exhibit various symptoms, including facial dysmorphisms and microcephaly, therefore, further analysis is required to clarify what kind molecules associate with the uncharacterized domain of TRRAP (1031–1159 amino acids)." (PMID 34934055, 2021). "Other phenotypes, such as microcephaly (7/24 individuals), hearing impairment (3/24 individuals) and visual impairment (4/24 individuals), were also observed in the patients, who presented various clinical spectra associated with TRRAP pathogenic missense variants." (PMID 34934055, 2021).
neuropathies (1 paper, 2021). "These basic and clinical studies point to a potential involvement of TRRAP in the manifestation of these neuropathies in humans." (PMID 33594975, 2021).
pancreatic tumours (1 paper, 2024). "A comparison with KPC cells revealed that only RUVBL1, RUVBL2, TRRAP, SPT6 and WDR5 were essential in pancreatic tumours and more important for KPC cells than fibroblasts (Δlog2FC<0)." (PMID 38821858, 2024).
Telangiectasia (1 paper, 2022). Telangiectasias refer to small dilated blood vessels located near the surface of the skin or mucous membranes, measuring between 0.5 and 1 millimeter in diameter. "TRRAP is a large and highly conserved protein of the PIKK family, which further comprises DNA-dependent protein kinase, ataxia–telangiectasia mutated, ataxia- and Rad3-related, mammalian target of rapamycin, and suppressor of morphogenesis in genitalia." (PMID 35151693, 2022).
thyroid cancer (1 paper, 2013). "The present study reports for the first time the mutational status of the GNA11, MMP27, FGD1, TRRAP and GRM3 genes in thyroid cancer." (PMID 24137342, 2013). "Mutations were not identified in the TRRAP gene in 12 thyroid cancer cell lines and 16 PTC tumor samples." (PMID 24137342, 2013). "The mutation status in the GNA11, MMP27, FGD1, TRRAP and GRM3 genes has not been studied in thyroid cancer." (PMID 24137342, 2013). "This suggests that TRRAP and GRM3 may not have important roles in the pathogenesis of this type of thyroid cancer." (PMID 24137342, 2013). "In conclusion, the present findings suggested that genetic alterations in the GNA11, MMP27, FGD1, TRRAP and GRM3 genes may not be significant in the tumorigenesis of thyroid cancer." (PMID 24137342, 2013).
cancer (30 papers, 2013 to 2026). A tumor composed of atypical neoplastic, often pleomorphic cells that invade other tissues. "Transformation/transcription domain-associated protein (TRRAP) has been reported to stimulate the tumorigenic potential of cancer cells and induce the gene transcription of NANOG." (PMID 37047234, 2023). "Unexpectedly, the TRRAP mutations found in human cancers are largely centered on the Tra1 interaction surfaces mediating assembly of NuA4 and SAGA complexes, which also harbor several post-translational modifications (UniProtKB—Q9Y4A5)." (PMID 29559617, 2018). "In humans, the essential catalytic subunit Tip60, along with several other NuA4 subunits including TRRAP, are associated with tumorigenesis in different cancers such as colon, breast, and prostate tumors and are essential for stem cell maintenance and renewal." (PMID 29559617, 2018). "Cancer-linked mutations found in TRRAP are clustered in the NuA4/TIP60 assembly interface, which are also hotpots for post-translational modifications." (PMID 29559617, 2018). "Taken together, our findings indicate that ECGC efficiently disrupts c-MYC:TBP and c-MYC:TRRAP complex formation in cancer cells." (PMID 38424045, 2024). "Four cancer driver genes, namely KMT2D, LRP1B, TRRAP, and FLNA, were identified in the 20 most frequently mutated gene sets." (PMID 37373553, 2023). "The biological relevance of the EP300 and TRRAP sites encompassing P-tripeptides is supported by the evidence that some of them are involved in genomic alterations reported in cancer patient-derived datasets on the cBioportal website." (PMID 37954147, 2023). "This study aimed to investigate the role of the TRRAP-NANOG signaling pathway in the tumorigenicity of cancer stem cells." (PMID 37047234, 2023). "We selected the MIR17-HG gene, which encodes an oncomir precursor, is a prominent target of MYC in cancer cells, and is activated by TRRAP in HCT116 cells." (PMID 35244540, 2022). "The MYC:TRRAP interaction is a MYC vulnerability in cancer and presents an opportunity for drug discovery." (PMID 34676047, 2021). "Since NANOG is essential for maintaining the cancer stem cell (CSC)-like traits of colon cancer spheroids, TRRAP may promote cancer spheroid development." (PMID 41227365, 2025). "The remaining most frequent mutated cancer driver genes found in early-stage samples (KMT2C, ALK, BRCA2, GRM, ATM, and BRCA1) were not among those found to be the most frequently shared in late-stage samples (MUC16, CSMD3, KNT2C, NF1, LRP1B, SPEN, and TRRAP)." (PMID 37446001, 2023). "The MYC:TRRAP interaction is critical for MYC function in promoting cancer." (PMID 31790487, 2019). "Our data suggest that the MYC:TRRAP interaction could have a lower free energy of association, and therefore is a more desirable target for inhibition of MYC function in cancer by small-molecules than the MYC:MAX interphase." (PMID 31790487, 2019). "These considerations warrant targeting the scaffolding function of TRRAP with small-molecule modulators, which may prove successful in preventing cancer and/or in killing cancer cells." (PMID 29559617, 2018).
cancer (continued). "In the remaining 56 small families without shared variants of HOXB13 and TRRAP, patients with PC from 44 families had at least one variant of cancer genes of the CGC." (PMID 27701467, 2016). "Furthermore, our analysis revealed a scarcity of cancer somatic mutations in the interfaces of complexes involving two oncogene products, NRF2 (the NRF2‐MAF1 interface) and TRRAP (interfaces involving the FAT domain of TRRAP), suggesting critical functions of these protein complexes in cancer cells." (PMID 37964489, 2024). "Therefore, TRRAP deregulation can potentially contribute to cancer development." (PMID 37954147, 2023). "This evidence highlights the crucial role played by SMYD3, TRRAP, and EP300 in cancer-related epigenetic reprogramming processes." (PMID 37954147, 2023). "TRRAP knockdown decreased the expression of CD44, a CSC marker that regulates self-renewal, tumor initiation, and cancer metastasis." (PMID 37047234, 2023). "We recently reported that the essential MYC cofactor TRRAP (Transformation/transcription domain-associated protein) forms a critical interaction within the MYC TAD, which may represent a viable strategy for targeting MYC in cancer by inhibiting MYC:TRRAP binding." (PMID 36018850, 2022). "With regard to their broad impact in cancer, our findings contribute to explain the pleiotropic functions of curcumin, and suggest that this natural spice, or more bioavailable derivatives thereof, may constitute useful adjuvants in the therapy of MYC-dependent and TRRAP-associated human tumors." (PMID 33937075, 2021). "GCN5 and TRRAP, other components of SAGA, interact with the MYC oncoprotein in mammalian cells, which is the most important protein in cancers." (PMID 29555684, 2018). "Therefore, the TAD of MYC, MB2, and MYC:TRRAP are required for MYC-driven transactivation and cancer promotion." (PMID 34676047, 2021). "Four CRs (TRRAP, EP300, NSD2 and MSH6) having synthetic lethal interactions with MAP2 were integrated as a MAP2 CSL module in COAD, where MAP2 was affected by two taxnes (Paclitaxel and Docetaxel).These four CRs play roles in cell cycle, notch signaling pathway and mismatch repair in human cancers." (PMID 36180906, 2022).
tumor (21 papers, 2011 to 2025). "Amplifications in the ALK, DYNC1I1, and TRRAP genes were found in one tumor, which also showed a point mutation in TERT (each 5%)." (PMID 40227833, 2025). "Pre- and post-treatment tumour biopsies for two patients identified temporal genomic heterogeneity, somatic mutations in the TRRAP gene, which encodes a PI3K-like protein kinase, and emergent somatic mutations related to protein kinase signalling." (PMID 33799597, 2021). "The transcription of important genes involved in angiogenesis, tumor survival, and cell proliferation can be amplified by coactivators like Mediator, TRRAP, and CBP/p300." (PMID 41155227, 2025). "Transplantation of TRRAP-silenced HCT-15 cells resulted in a significantly reduced tumor volume compared to control HCT-15 spheroid cells." (PMID 37047234, 2023). "Among these genes, BRCA1, RB1, RBAK and CSMD3 are tumour suppressors, while TRRAP functions as an oncogene." (PMID 35735060, 2022). "Further accumulation of mutations in ZNF521, TRRAP, and RBFOX1 result in the metastatic clade that forms the third subclone (marked in red), and mark the point of tumor dissemination to the liver." (PMID 34149820, 2021). "The elevated expression of CD247, FCGR1A and TRRAP were associated with superior OS and RFS of CHOL, indicating that the three tumor antigens have potential immune-stimulatory effects." (PMID 33685460, 2021). "Protein expression of TRRAP was low in BC compared with matched normal breast tissues, indicating a tumor suppressive role of TRRAP for BC." (PMID 27701467, 2016). "Knockdown of TRRAP sensitizes GSCs to apoptotic stimuli, decreases self-renewal and proliferation, and suppresses tumor formation in vivo, suggesting that TRRAP maintains GSCs in a stem cell-like state." (PMID 24212955, 2011). "Elevated TRRAP levels lead to increased expression of genes that drive tumour progression." (PMID 41179304, 2025). "To investigate whether TRRAP is important for tumor growth, we measured the in vivo tumorigenicity of HCT-15 spheroid cells in a xenograft transplantation model." (PMID 37047234, 2023). "TRRAP knockdown inhibited tumor growth and NANOG expression in the HCT-15 xenograft model." (PMID 37047234, 2023). "Furthermore, TRRAP knockdown significantly reduced tumor growth in a murine xenograft transplantation model, which could be reversed by NANOG overexpression." (PMID 37047234, 2023). "Moreover, TRRAP knockdown significantly reduced in vivo tumor growth of A2780 cells." (PMID 37047234, 2023). "Adding back NANOG abrogated the tumor growth suppressed by TRRAP silencing, suggesting the pivotal role of NANOG in TRRAP-mediated tumorigenesis." (PMID 37047234, 2023). "Three tumor antigens (CD247, FCGR1A, and TRRAP) correlated with superior prognoses and infiltration of antigen-presenting cells in CHOL were identified using narrow-down analysis, thus promising candidates for mRNA vaccine." (PMID 33685460, 2021).
tumor (continued). "In contrast, mutant BRAF, ATM, LRP1B, FAT4, FMN2, TRRAP, and ROS1 had higher stromal score (except ATM), immune score and ESTIMATE score, and the tumor purity was lower than the wild-type." (PMID 33836681, 2021). "Together, three tumor antigens (CD247, FCGR1A, and TRRAP) were identified as potential candidates for the CHOL-mRNA vaccine with potential immune provocative effects and can be processed and presented by antigen-presenting cells (APCs) to induce a tumor response." (PMID 33685460, 2021).
neurodevelopmental disorder (3 papers, 2022 to 2026). A behavioral and cognitive disorder with onset during the developmental period that involves impaired or aberrant development of intellectual, motor, or social functions. "Instead, we identified several rare, likely pathogenic variants in seven genes implicated in neurodevelopmental disorders: KLHL17, TDO2, TRRAP, EIF3F, ATP10A, DICER1, and CDH15." (PMID 35743796, 2022).
infection (2 papers, 2016 to 2018). The state of being infected such as from the introduction of a foreign agent such as serum, vaccine, antigenic substance or organism. "The ability of these FH-tagged E1A 1-80 proteins to interact with p300 and TRRAP was examined by infection of HeLa cells with these Ad vectors, followed by immunoprecipitation of the cell lysates with Flag antibody beads and Western blot analysis with the indicated antibodies." (PMID 27382434, 2016).
TRRAP also shares sentences with these, for which no sentence is quoted: childhood disintegrative disorder (2 papers); glioma (2); major depression (2); anemia (1); angiosarcoma (1); autism spectrum disorder (1); Autosomal Dominant Non-Syndromic Hearing Loss (1); brain tumour (1); breast tumors (1); calculus (1); ciliopathies (1); Colon (1); epilepsy (1); goblet cell adenocarcinomas (1); kidney cancer (1); leukemia (1); lung adenocarcinoma (1); medulloblastoma (1); mucinous adenocarcinoma of the appendix (1); neuroendocrine carcinoma (1); neuroendocrine tumors (1); neurological disorders (1); obsessive-compulsive disorder (1); oral diseases (1); papillorenal syndromes (1); periodontal diseases (1); polymicrogyria (1).